NOG (noggin)
Diseases named in the same sentence as NOG in open-access papers (continued):
Sharing a sentence is not in itself a finding about the gene and the disease.
long bone fractures (1 paper, 2011). "A total of fifteen SNPs within four genes of the Bone Morphogenetic Protein (BMP) pathway (BMP-2, BMP-7, NOGGIN and SMAD6) were examined, in 109 randomly selected patients with long bone fractures as a result of motor vehicle accident, fall or direct blow." (PMID 21310029, 2011).
metastatic tumors (1 paper, 2023). "To evaluate clinical relevance of these findings, we performed immunohistochemical staining for Noggin using tumor samples obtained from two patients whose surgical tissues were obtained from pairs of primary lung tumors and brain-metastatic tumors." (PMID 38012621, 2023).
Myocardial fibrosis (1 paper, 2025). "Additionally, members of the transforming growth factor-beta (TGF-β) superfamily (INHBA, INHBB, NOG) occupy central positions in the protein interaction network, reflecting the dual role of the TGF-β pathway (regulating myocardial fibrosis and vascular plaque stability) at different disease stages." (PMID 41283645, 2025).
non-small cell lung carcinoma (1 paper, 2020). A group of at least three distinct histological types of lung cancer, including non-small cell squamous cell carcinoma, adenocarcinoma, and large cell carcinoma. "It has been shown that prostate and non-small cell lung cancer (NSCLC) cell lines overexpressing Noggin show decreased growth/expansion capabilities in a xenograft mouse model." (PMID 32486027, 2020).
optic atrophy (1 paper, 2016). A disorder characterized by loss of optic nerve fibers. "Our results suggest that apoptosis mediated by OPA1 mutations plays an important role in the pathogenesis of optic atrophy, and both noggin and β-estrogen may represent potential therapeutic agents for OPA1-related optic atrophy." (PMID 26738566, 2016). "However, both noggin and β-estrogen can rescue this phenotype, suggesting apoptosis mediated by OPA1 mutations plays an important role in the pathogenesis of optic atrophy, and noggin and β-estrogen could be potential therapeutic agents." (PMID 26738566, 2016).
osteosarcoma (1 paper, 2024). A usually aggressive malignant bone-forming mesenchymal neoplasm, predominantly affecting adolescents and young adults. "Besides, Noggin can specifically activate FGFR2 in osteosarcoma cells." (PMID 38509118, 2024). "Taken together, we revealed for the first time that Noggin enhances phosphorylation of FGFR2 in both adipose-derived stem cells and osteosarcoma-derived osteoblastic cells and activates FGFR2/Src/Akt and ERK intracellular signaling pathway in adipose-derived stem cells." (PMID 38509118, 2024).
otosclerosis (1 paper, 2023). Formation of spongy bone in the labyrinth capsule which can progress toward the stapes (stapedial fixation) or anteriorly toward the cochlea leading to conductive, sensorineural, or mixed hearing loss. "Importantly, mutations in noggin, which is an inhibitor of several BMPs, are associated with multiple-synostoses syndrome whose otologic presentation mimics otosclerosis and is characterized by stapes fixation." (PMID 36653343, 2023).
ovarian carcinoma (1 paper, 2009). A malignant neoplasm originating from the surface ovarian epithelium. "Preliminary results shown here with Noggin and by others using Noggin and Chordin support the potential therapeutic role of these antagonists in ovarian cancer progression through the inhibition of BMP signaling." (PMID 19366455, 2009). "Previous results using Noggin and Chordin support the potential therapeutic role of these antagonists in ovarian cancer progression through the inhibition of BMP signaling." (PMID 19366455, 2009).
polyarticular JIA (1 paper, 2024). "In polyarticular JIA FLS, Col2 (FC = 1.27; p < 0.000) protein concentration significantly increased in cells treated with noggin compared to untreated cells." (PMID 38166938, 2024).
pulpitis (1 paper, 2025). Inflammation of the dental pulp. "Furthermore, these factors and miR-200c appear to mutually influence each other, suggesting that the observed downregulation of miR-200c in the pulpitis pulp tissue and inflamed dental pulp cells may be attributed to the upregulation of noggin and proinflammatory cytokines." (PMID 40724983, 2025).
rhabdomyosarcoma (1 paper, 2019). A rare aggressive malignant mesenchymal neoplasm arising from skeletal muscle. "Co-localization of antibodies to G8, noggin, filensin and CP49 was observed in most RC13 and a subpopulation of RD human rhabdomyosarcoma cell lines." (PMID 30973903, 2019).
schwannoma (1 paper, 2014). A benign, usually encapsulated slow growing tumor composed of Schwann cells. "The analysis of noggin expression in a subset of schwannomas may provide a novel diagnostic tool for schwannoma." (PMID 24959229, 2014). "Furthermore, the radiological bone scalloping and erosion observed in schwannoma patients may be caused by schwannoma-derived noggin." (PMID 24959229, 2014). "In addition, noggin may have potential as a novel molecular and diagnostic marker for identifying certain types of schwannoma." (PMID 24959229, 2014). "In the schwannoma tissue samples, various levels of noggin immunoreactivity were observed in two of the five tissues." (PMID 24959229, 2014). "Noggin mRNA expression was found to be significantly increased in the schwannoma tissue compared with the other soft tissue tumors (P<0.05)." (PMID 24959229, 2014). "In the present study, to investigate the pathomechanism of bone resorption, the expression of noggin (a potent antagonist of bone morphogenetic protein) was analyzed in schwannoma tissues and compared with that observed in other soft tissue tumors." (PMID 24959229, 2014). "Schwannoma tissue extracts containing the noggin protein were found to inhibit osteoblastic differentiation in MC3T3-E1 cells, resulting in a dose-dependent reduction in ALP activity." (PMID 24959229, 2014). "In the present study the expression of noggin in soft tissue tumor samples, including schwannomas, was analyzed." (PMID 24959229, 2014). "Quantitative polymerase chain reaction analysis revealed that the mRNA levels of noggin in schwannomas were significantly increased compared with the levels in other tumors." (PMID 24959229, 2014). "In conclusion, the present study has detected the expression of noggin in schwannoma tissue samples." (PMID 24959229, 2014). "Western blot analysis in the schwannoma tissue revealed a single immunoreactive band corresponding with the size of the noggin protein, with a molecular mass of 26 kDa." (PMID 24959229, 2014). "The present study detected the expression of noggin in schwannomas using RT-PCR analysis, immunohistochemistry and western blot analysis." (PMID 24959229, 2014). "The gene product of noggin was only detected in a subset of schwannomas using immunohistochemistry and western blot analysis." (PMID 24959229, 2014). "The expression of noggin mRNA and protein was examined and the effect of the tissue extract from a noggin-producing schwannoma for BMP-induced osteoblastic differentiation in vitro was investigated." (PMID 24959229, 2014). "Table II shows the clinical data of the patients with schwannomas and the noggin expression patterns in the schwannoma samples obtained from these patients." (PMID 24959229, 2014). "Although the expression of noggin in neurogenic tumors, including schwannomas, has yet to be investigated, this type of tumor may produce noggin given their neurogenic cellular origin." (PMID 24959229, 2014). "Furthermore, RT-PCR analysis revealed that noggin mRNA levels were greatest in the schwannoma tissue and the second highest in the malignant neurogenic tumor tissue." (PMID 24959229, 2014). "Furthermore, the tissue extract from a noggin-producing schwannoma was found to inhibit osteoblastic differentiation in MC3T3 mouse osteoblastic cells in a dose-dependent manner." (PMID 24959229, 2014). "The findings of the present study indicate that schwannoma-derived noggin may induce a negative balance of bone remodeling via its BMP antagonist activity, resulting in local bone resorption." (PMID 24959229, 2014).
soft tissue tumors (1 paper, 2014). "Table I shows the immunohistochemical analyses of the noggin protein in the soft tissue tumors." (PMID 24959229, 2014). "Noggin may be a useful molecular marker for the differential diagnosis of soft tissue tumors in pathology." (PMID 24959229, 2014).
spindle cell rhabdomyosarcoma (1 paper, 2019). An uncommon variant of rhabdomyosarcoma characterized by the presence of whorls of spindle cells forming a storiform pattern. "Human alveolar, embryonal, pleomorphic and spindle cell rhabdomyosarcomas and Wilms tumors contained a subpopulation of cells immunoreactive for G8, noggin, MyoD and beaded filaments." (PMID 30973903, 2019).
symphalangism (1 paper, 2009). "The importance of NOG for the development of joints was shown by the identification of mutations in NOG in patients with symphalangism (SYM1, MIM #185800) and multiple synostosis syndrome (SYNS1, MIM #186500)." (PMID 19956691, 2009).
Wilms tumor (1 paper, 2019). An embryonal neoplasm characterized by the presence of epithelial, mesenchymal, and blastema components. "RMS and Wilms tumors contain cells immunoreactive for both G8 and noggin." (PMID 30973903, 2019).
tumor (29 papers, 2009 to 2025). "According to our in silico analyses, BMP‐9‐mediated induction of ID1 should have tumour‐suppressive effects, while noggin should cause tumour‐promoting changes." (PMID 34841646, 2022). "An in vivo study with transgenic mice overexpressing Noggin showed that overexpression resulted in a loss of the normal crypt-villus architecture along with de novo crypt formation and neoplasia." (PMID 32486027, 2020). "Besides, high Noggin expression in the invasive front of the tumor was independently and significantly associated with prognosis." (PMID 34001012, 2021). "In addition, other BMP-antagonists, including Dand5 and noggin, have been linked to tumor progression and metastasis." (PMID 31694641, 2019). "However another study has found that noggin can promote skin tumorigenesis via stimulation of the Wnt and Shh signaling pathways, so the precise molecular mechansims underlying tumor formation in our animals remain unclear." (PMID 22168923, 2011). "Due to the tumour suppressive nature of BMP signalling, Noggin has been implicated in a wide variety of cancers, including breast, gastric, colorectal, and skin tumorigenesis." (PMID 40212011, 2025). "As with most tumor organoids, the addition of common growth factors such as wnt-3a, noggin, R-spondin-1 to MPMO culture is beneficial to its development." (PMID 38200517, 2024). "Overall, BMP‐9 stimulation of organoids promoted an enrichment of tumour‐suppressive gene expression signatures, whereas the stimulation with noggin had the opposite effects." (PMID 34841646, 2022). "In vivo and in vitro suppression of the BMP signaling pathway with Noggin suppress the capability of CA-MSCs to support tumor growth and tumor stemness." (PMID 35251985, 2022). "Considering the invasive front and tumor center, the high expression of Noggin was similar in the invasive front (n = 90, 55.2%) and the tumor center (n = 91, 55.8%)." (PMID 34001012, 2021). "Noggin expression at the invasive front and tumor center was significantly decreased in advanced T stage, non-intestinal-type (invasive front, P = 0.008 and P < 0.001; tumor center lesion, P = 0.013 and P = 0.001)." (PMID 34001012, 2021). "RBPMS2 protein expression was high at the tumor center (n = 86, 52.8%) and low at the invasive front (n = 69, 42.3%), while Noggin protein expression was high in both tumor center (n = 91, 55.8%) and the invasive front (n = 90, 55.2%)." (PMID 34001012, 2021). "Further, the investigated proteins showed significant associations between Noggin and RBPMS2 proteins in the invasive front as well as the tumor center (P < 0.001)." (PMID 34001012, 2021). "High expression of Noggin was observed in 72 (61.3%) patients at both tumor center and invasive front." (PMID 34001012, 2021). "Testing the potential of G8+ RMS cells to give rise to tumors and the effects of depleting G8+/noggin+/BF+ cells on tumor expansion will be required before assigning them a pathogenic role in RMS." (PMID 30973903, 2019). "The immunostaining for noggin was localized to the cytoplasm of the spindle tumor cells, primarily demonstrating an Antoni B tissue pattern." (PMID 24959229, 2014). "Specifically, we found that inhibition of BMP signaling by overexpression of Noggin in hair follicles resulted in formation of tumors that resemble trichofolliculomas, a relatively uncommon hair follicle-derived neoplasia." (PMID 22168923, 2011). "We found that overexpression of Noggin in P-cadherin positive hair progenitor cells led to benign hair follicle-derived neoplasias resembling human trichofolliculomas." (PMID 22168923, 2011). "In the late phase of the experimental observation, concomitantly to bone repair, noggin silencing in cancer cells also reduces tumor growth." (PMID 21249149, 2011). "It will be of great interest to test Noggin, Chordin, Cerberus or Gremlin as in vivo potential tumor suppressors in xenograph models." (PMID 19366455, 2009).
tumor (continued). "Interestingly, these functions seem to be more or less conserved in the T‐Orgs, implying that the effects of BMP‐9 (as well as noggin) should remain similar in normal as well as tumour epithelium." (PMID 34841646, 2022). "Therefore, noggin is understood to be tumour‐promoting through its reduction in ID1 expression, while BMP‐9 is understood to be tumour‐suppressive in how it shifts the ID1/NOG ratio in a favourable direction." (PMID 34841646, 2022). "Interestingly, the expression of the Noggin protein at the invasive front is strongly correlated with prognostic factors, compared with those at the tumor center." (PMID 34001012, 2021). "Low Noggin expression at the invasive front and tumor center lesion was significantly correlated with advanced T stage and non-intestinal GC (invasive front, P = 0.008 and P < 0.001; tumor center lesion, P = 0.013 and P = 0.001, respectively)." (PMID 34001012, 2021). "The elevated expression of Noggin at the invasive front was significantly associated with longer OS (P = 0.029), but not at the tumor center lesion (P = 0.476)." (PMID 34001012, 2021). "Lastly, we identify the BMP signaling pathway as a potential effective therapeutic strategy to treat ACVR1 R206H mutant DIPGs as exogenous Noggin expression at tumor initiation or treatment with LDN212854 significantly increases tumor latency and prolongs survival." (PMID 30833574, 2019). "Consistently, the expression of the BMP antagonist noggin seems to be restricted to those tumor cells that preferentially induce osteolytic bone metastasis, while the forced expression of noggin in osteosclerotic PCa cells inhibited their ability to induce osteoblast metastases." (PMID 24971315, 2014). "Importantly, mating these mice with BMP4 transgenic mice under the same promoter rescued the tumor phenotype indicating that inhibition of BMP signaling mediated the effects of the noggin transgene." (PMID 22168923, 2011). "Furthermore, intra-osseous tumor growth of noggin-silenced PC-3 cells was limited, most probably as a result of the persisting osteoblast activity." (PMID 21249149, 2011). "For example, it is well-established that TGF-βR inhibition (by eg, A-8301 and Noggin) critically affects fibroblast biology, thus potentially masking physiologically relevant CAF phenotypes and crosstalk with the tumor cells." (PMID 36868311, 2023). "We first grew organoids from the tumor tissue and found that they exhibited Wnt-, CHIR-99021-, and noggin-independent growth." (PMID 37230989, 2023). "The expression of NOG and S1PR1 genes was also increased in CFP1-deleted tumor tissue cells, while the expression of RASSF9 and BST2 was decreased significantly." (PMID 35864225, 2022). "The prognostic value of stroma-related proteins, Noggin and RBPMS2, expressed in the tumor center or invasive front, is complex and debatable." (PMID 34001012, 2021). "The expression of Noggin and RBPMS2 proteins in tumor cells at the tumor center and invasive front of resected GC was evaluated by immunohistochemistry, and in conjunction with clinicopathological parameters the patient survival was analyzed." (PMID 34001012, 2021). "In the HONE-1 and AGS cell lines, treatment of Neo control cells with Noggin had a marked positive effect on migration, suggesting that BMP signalling in these cells, albeit at a low extent, is tumour-suppressive." (PMID 32708289, 2020). "When BMP-2 action is down-regulated by treatment with the BMP antagonist, noggin, PC3 cells have less migration and invasion in vitro and less tumor formation in vivo." (PMID 23977121, 2013).
tumor (continued). "Weekly monitoring and quantification of intra-osseous tumor growth by BLI revealed that, in both experiments, noggin suppression in cancer cells had a moderate impact on their proliferation in vivo." (PMID 21249149, 2011). "Therefore, we evaluated the expression of Noggin and RBPMS2 proteins in the tumor center and invasive front of resected GC and compared their relationship with clinicopathological parameters and clinical outcomes." (PMID 34001012, 2021). "The basal culture conditions used for short-term organoid formation do not maintain the long-term viability of SCLC tumor organoids, and this was not improved by the addition of Noggin or A8301." (PMID 33572899, 2021). "Osteolytic cancer cell-derived noggin may antagonize endogenous, osteoblast-derived BMP-7 and, therefore, allow escape from its inhibitory effect on tumor growth." (PMID 21249149, 2011). "High Noggin protein expression and EBV positivity at the invasive front were significantly correlated with better OS (P = 0.030 and P = 0.020), but not the high Noggin protein expression in tumor center lesions and RBPMS2 protein expression at the invasive front and tumor center." (PMID 34001012, 2021). "Multivariate analysis revealed that high Noggin protein expression of the invasive front was an independent prognostic factor for overall survival (hazard ratio [HR], 0.58; 95% confidence interval [CI]; 0.35–0.97, P < 0.036), but not at the tumor center (HR, 1.35; 95% CI; 0.81–2.26, P = 0.251)." (PMID 34001012, 2021). "To further prove that the observed tumor phenotype is BMP signaling dependent, not due to the nonspecific positional effort of transgene integration, we generated Nse-BMP4;Nse-Noggin double transgenic mice by mating Nse-BMP4 with Nse-Noggin mice." (PMID 22168923, 2011).